OAS2 (2'-5'-oligoadenylate synthetase 2)
Diseases named in the same sentence as OAS2 in open-access papers (continued):
Sharing a sentence is not in itself a finding about the gene and the disease.
infection (continued). "On the other hand, PRRSV could inhibit IFN-mediated JAK-STAT signaling pathways to interrupt ISG transcription; for example, ISG15, ISG56, CCL2, MX1, OAS2, and RNaseL of PAMs were significantly downregulated after infection with the PRRSV strain VR2385." (PMID 27182980, 2016). "During E30 infection, genes associated with the type I IFN signaling pathway (Isg15, Mx1, Mx2, Sp100, Ifit1, Ifit3, Ifih1, Irf7, Irf9, guanylate-binding proteins 2 [Gbp2], and Stat1) and defense response to viruses (Ddx58, Ddx60, Zbp1, Oas2, Nlrc5, and Eif2ak2) were significantly upregulated." (PMID 36147849, 2022). "Since Mx1, Oas1, and Oas2 were upregulated in cells that O. tsutsugamushi preferentially targets for replication (endothelial cells and MΦ), future studies utilizing knockdown or genetic deletions of these molecules are needed to delineate their role during infection." (PMID 36678402, 2022). "In contrast, infection of A459ACE2 cells with NL63 robustly induced IFNB and IFNL1 as well as IFIT1 and OAS2 by 48 hpi." (PMID 41369222, 2026). "The induction levels of antiviral genes—including DDX58, OAS1, OAS2, ISG15, MX2, IFI44L, RTP4, and IFNB1—were markedly reduced in KO cells compared to WT cells post-infection." (PMID 40872812, 2025). "Differential gene expression analysis in hROs at 24 h post-infection revealed a robust upregulation of antiviral genes (e.g. IFIT1, IFIT2, MX1, and OAS2) and pathways related to antiviral innate immunity and viral replication in rRVFV versus mock comparisons." (PMID 41255708, 2025). "Specifically, upon infection with West Nile, Sindbis, Influenza, or Vaccinia viruses, OAS3 plays the dominant role in RNase L activation, while OAS2 fulfills that role in the context of Zika virus infection." (PMID 40312500, 2025). "For this purpose, PBE cells were challenged with SIV H1N1 or H3N2 and the expression of IFN-β and the antiviral factors Mx1, Mx2, IFITM1, OAS1, OAS2, and OASL were evaluated at different hours post-infection." (PMID 40565228, 2025). "Consistently, knockdown of PCGF3 increased the expression levels of ISGs (ISG15, IFIT1, OAS2, MX1 and IRF7) and IFNB1, and decreased the VSV replicates (RNA level and virus titer) after VSV infection." (PMID 39368978, 2024). "Infection with 60 ng/ml of HIV-1 for 24 or 48 h resulted in a significant increase in the expression of OAS1, OAS2, OAS3, and OASL at the mRNA level." (PMID 37209263, 2023). "Our data suggest that human OAS1, OAS2, and RNase L are each essential for the correct regulation of immunity to SARS-CoV-2 but are otherwise largely redundant in natural conditions of infection." (PMID 36538032, 2023). "The few proteins for which a fold-change >2 or <−2 was observed 48 h after infection are involved in apoptosis (SCARF1, PLSCR3), ubiquitination (UBE2E3, OTULIN), or the response to type I IFN (OAS2)." (PMID 35337059, 2022). "The transcription levels of OAS2, RIG-I, and IFN-β during VSV-Sp100A infection were significantly reduced in PKM2kd cells compared to HEp-2 cells." (PMID 36383022, 2022). "In parallel with the induction of STAT1 expression, transcription of some IFN stimulated genes (ISGs) was also noticed upon USUV infection of JAR cells, such as OAS2 and ISG15." (PMID 35893684, 2022). "In contrast, the BPH-1 cells are strong inducers of IFN-I at a high multiplicity of infection and respond to IFN-I after P/V/F mutant infection, with induction of three key ISGs (OAS2, IFIT1 and TLR3), indicating the establishment of an anti-viral state." (PMID 35631014, 2022). "P/V/F mutant infection upregulates expression levels of OAS2 by ~40 fold and TLR3 expression by ~15 fold, respectively, with only modest gene expression changes seen with the WT infection." (PMID 35631014, 2022). "Levels of ISG mRNAs were variable, with SARS-CoV-2 inducing moderate levels of OAS2 and IFIT1 mRNAs, but only late in infection (48 hpi), similar to those induced by SINV at 24 hpi." (PMID 33811184, 2021).
infection (continued). "Per bin, the intron counts of the infection-induced genes IFIT2, OAS2, CCL5, IL6, NFKBIA, and TNF are shown, along with ATXN10 as control." (PMID 33585804, 2021). "Within the antiviral category, the oligoadenylate synthase-like proteins (OASL1 and OASL2) increased in protein abundance at 8- and 24 hr post-infection, and OAS proteins (OAS1a and OAS2) increased at 24 hr post-infection." (PMID 31951200, 2020). "In contrast to the minimalincreases observed during WT MERS-CoV infection over mock-infected cells,MERS-ΔNS4a or MERS-ΔNS4ab infection resulted in significantly elevatedlevels of IFNL1 mRNA and representative ISG OAS2 andIFIT2 mRNAs." (PMID 30914508, 2019). "Total cellular RNA was extracted at 3, 6, 9, 12, 24, 48, and 72 h after infection, and the abundance of HCV RNA and mRNA levels of the ISGs MX1, SOCS3, IFNβ, and OAS2 were quantified by qRT-PCR." (PMID 31138826, 2019). "Infection of T-HESC strongly upregulated the expression of bioactive IFN-β and of related ISGs (MXA, OAS2)." (PMID 28281680, 2017). "We found that cells from people with the Neandertal-like haplotype express lower levels of OAS3 upon infection, as well as distinct isoforms of OAS1 and OAS2." (PMID 27899133, 2016). "Within metabolic inflammation, convergent evidence also implicates the IFN-OAS axis in T2DM: in human skin and skeletal muscle transcriptomes, OAS1/OAS2/OAS3 are significantly upregulated and enriched for infection-related pathways, indicating tissue-level activation of interferon responses in T2DM." (PMID 41569989, 2026). "Noteworthy, two ISGs were further upregulated 24 h post-infection in M1-MDMs: ISG20 and OAS2." (PMID 39940721, 2025). "Finally, at 72 hours post-PIV3 infection, the transcriptional response remains robust and interferon-centric, with continued expression of IFIT1, IFIT2, IFIT3, MX1, and OAS2." (PMID 39591472, 2024). "In cluster 1, OAS2, IFIT3, IFI16, and DDX58 were higher in the rmIFNγR1-Ig treated animals at day 7, despite this cluster of genes being defined as genes that are highly induced at day 3 post-infection." (PMID 38950078, 2024). "Finally, at 72 hours post-PIV3 infection, the transcriptional response remains interferon-centric, with continued expression of IFIT1, IFIT2, IFIT3, MX1, and OAS2." (PMID 39591472, 2024). "In the context of infection, ORF4a antagonizes IFN production and signaling, as A549DPP4 cells infected with a recombinant MERS-CoV-Δ4a showed increased mRNA expression levels of interferon lambda (IFNL1) and ISGs OAS2 and IFIT1." (PMID 37197199, 2023). "Interestingly, this increase was gradually reduced over time, and only OAS2 and OAS3 showed a slight increase in mRNA expression after 72 h of infection as compared to mock infection." (PMID 37209263, 2023). "Similar to Gbp7, Oas2 could also be induced by IFN and serve a role in host defense against infection." (PMID 36421815, 2022). "Hence, PKM2kd cells or HEp-2 cells were mock infected or infected with VSV-GFP or VSV-Sp100A, and the expression levels of OAS2, RIG-I, and IFN-β during infection were quantified by quantitative PCR (qPCR)." (PMID 36383022, 2022). "Some of the genes that were similarly modulated by MR766 and Rio-U1 related to cytokine signaling (CXCL10/11, CCL8) and the IFN response (IFIT2, ISG15, OAS2, DDX58, among others), suggesting some degree of similarity in signaling patterns following infection with either virus." (PMID 33405202, 2021). "Interestingly, while the bOas2 gene has two adjacent ISREs and bOas2 mRNA expression is induced only 4- to 6-fold, the human Oas2 has one ISRE and yet the expression of OAS2 mRNA is highly induced (10,000-fold) during infection of human cells." (PMID 31719180, 2019). "Interestingly, our RT-qPCR data reveals that the meta-genes ATOX1, OAS2 and USP18 were consistently up-regulated with a distinct pattern with infection time-course in THP-1 cells infected with DENV-1 or DENV-2." (PMID 27651116, 2016).
infection (continued). "Components of interferon pathway and innate immunity (IFI44L, IFITM3, MX1, IRF7, OAS2, STAT2, etc.)are significantly upregulated in the acute phase of infection, while the expression levels of genes involved in translational elongation and protein biosynthesis are decreased." (PMID 26070066, 2015). "Interestingly, at early time point post infection, activation of STAT1 signaling promoted expression of OAS-2 and Mx1." (PMID 24391501, 2014). "On the other hand, no significant change in the induction of OAS-2 and Mx1 was observed in these cells at late time points post infection." (PMID 24391501, 2014). "According to previous reports, during infection with several RNA viruses, NOD2 is activated and leads to the activation of a protective innate immune response mediated by interactions with adaptors including RIP2, MAVS, OAS2, CARD9, etc., resulting in activities against the pathogens." (PMID 38668261, 2024). "Interestingly, the expression of MX2, IFIT2, OASL and OAS2 was up-regulated after infection with HEV-3f in both pig livers and HepaRG cells but not in pig livers infected with HEV-3c." (PMID 38058490, 2023). "Specifically, infection of MAGI1-null ECs with IAV upregulates expression of signal transducer and activator of transcription 1 (STAT1), interferon b1 (IFNb1), myxovirus resistance protein 1 (MX1) and 2′-5′-oligoadenylate synthetase 2 (OAS2), and activate STAT5." (PMID 36082118, 2022). "In addition, the type 1 IFN related genes (OAS1G, OAS2, OASL1, OASL2, S100A6, S100A8, S100A9, S100A11) that are necessary for activation of the inflammasome in Francisella novida-infected macrophages, were highly induced over the course of infection and peaked at 24 hpi." (PMID 21110886, 2010). "For example, CD4+ T cells, but not monocytes, upregulated OAS1, OAS2, and DDX58 upon infection in all animals." (PMID 38317183, 2024). "In contrast to changes in mRNA levels, protein levels of OAS2 and OAS3 remained elevated in infected pericytes even after 48 and 72 h post infection, and OASL protein expression did not change as the result of infection." (PMID 37209263, 2023). "VSV-Sp100A infection in PML−/− and Sp100−/− cells induced significantly higher levels of transcription from RIG-I, OAS-2, IFI16, and IFN-β genes than VSV-GFP did but not transcription from the control gene c-myc." (PMID 36383022, 2022). "SARS-CoV-2 induced phosphorylation of STAT1, as well as rapid IFIT1 and OAS2 mRNA induction, suggest a similar host response to SARS-CoV-2 as that observed during mutant MERS-CoV-ΔNS4ab infection, and not that of WT MERS-CoV infection." (PMID 33811184, 2021). "Regardless of dexamethasone treatment or time post-infection, expression of ISGs of the OAS family, specifically OAS2, OAS3 and OASL, and its downstream RNaseL, were highly upregulated." (PMID 31635289, 2019). "Sindbis virus (SINV) or vaccinia virus (VACVΔE3L) infection of wild-type (WT) or OAS1-KO (knockout), OAS2-KO, or MAVS-KO RoNi/7 cells, but not RNase L-KO or OAS3-KO cells, induces robust RNase L activation." (PMID 31719180, 2019). "Expression of eight of these genes (IFIH1, OAS2, IFIT1, IFIT2, IFIT3, IFIT5, USP18 and DDX58F) was significantly elevated in response to VSV-ΔM51 infection in permissive cells, but not in resistant PDACs." (PMID 27533247, 2016). "Thus, activation of RNase L during VACVΔE3L infection of bat RoNi/7 cells was dependent on RNase L and OAS3 but not OAS1, OAS2, or MAVS, similar to our findings with SINV." (PMID 31719180, 2019).
tumor (29 papers, 2015 to 2025). "Another four genes, GBP1, GBP5, LY6E and OAS2, have also been reported to be associated with a variety of other tumor progression." (PMID 33223511, 2020). "In addition, the innate immune response‐associated genes, including Oas1a, Oas2, Oas3, Ifi202b, Irf7, and Tlr9, were all down‐regulated, indicating a deficiency in anti‐tumor immune response." (PMID 31602788, 2019). "The Tumor-3 subcluster was interestingly enriched for ISGs, such as interferon-induced guanylate-binding protein Gbp family members and Oas2." (PMID 41332581, 2025). "Several ISGs such as GBP family genes Gbp4 and Gbp5, Cxcl9, Oas2, and Stat1, were significantly downregulated in the old Tumor-3 subcluster." (PMID 41332581, 2025). "Pathway analyses indicated a difference in inflammatory response between the two primary tumours, with upregulation of OAS2, CCL2, and AKAP13 in Patient 1 compared to Patient 2 across all cell populations." (PMID 40438247, 2025). "For instance, the male-amplifier cg12560128 was negatively correlated with OAS2 and OAS3 in COAD, both known immune biomarkers linked to the tumor microenvironment." (PMID 39716176, 2024). "A cautionary finding was that in nulliparous mice activation of OAS2 resulted in more rapid primary tumor progression, suggesting that in nulliparous women the use of interferon-inducing agents should be carefully examined, especially for local recurrences." (PMID 35505346, 2022). "Priming with CpG attenuated Il6 and Nlrp3 expression, further upregulated expression of Nod2, Oas2, RhoA, Pycard, Tlr1/2 and Il12, and enhanced T-cell number and activation while polarizing macrophages to an anti-tumor phenotype." (PMID 33441763, 2021). "Extracellular OAS2 has also been reported as a negative regulator of T-cell function in oral cancer, promoting tumour progression by modulating anti-tumour immune response." (PMID 27572959, 2016). "Therefore, our findings indicated that OAS2 is involved in gefitinib resistance as a tumor suppressor." (PMID 36471952, 2022). "Specifically, in the tumor from patient #7, genes involved in T cell activation and signaling such as PTPRC (which encodes CD45), LCP2, FYB, CD3E, and LCK, and in genes involved in immune response and interferon signaling such as STAT1, OAS2, and HLA were downregulated." (PMID 37620318, 2023). "Interestingly, neutrophils exhibited the highest correlation with OAS members (cor = 0.268 in OAS1; cor = 0.42 in OAS2; cor = 0.371 in OAS3; cor = 0.332 in OASL), highlighting the key role of OAS members associated with neutrophils in tumor immune infiltrating cells." (PMID 32560641, 2020). "This trend was similarly observed at the protein level, as Western blot results indicated significant upregulation of CXCL10, CXCL11, OAS2, MTIE, and MTIX in tumor tissues, although FAT1 exhibited an opposite trend compared to the qPCR results." (PMID 40574841, 2025). "qRT-PCR revealed significant upregulation of CXCL10, CXCL11, ME1, MT1X, FAT1, OAS2, and MT2A in tumor tissues compared to normal tissues." (PMID 40574841, 2025). "Our co-expression analysis indicated a significant and strong positive correlation between the expression of all selected PARPs, OAS2 and IFIT1 in tumor tissue suggesting a coregulatory mechanism within the tumor microenvironment." (PMID 40646573, 2025). "As a tumor suppressor, OAS2 is related to gefitinib resistance that DUXAP10 recruits EZH2 epigenetically silencing OAS2." (PMID 40701777, 2025). "We observed a small cluster of tumor cells (c9) that exhibited a gene expression pattern (OAS1, ISG15, OAS2) consistent with an interferon (IFN) response gene signature." (PMID 37609233, 2023). "Previous studies also reported that IFI44L, TRIM22, OAS1, OAS2, and MX2 inhibited tumor proliferation and metastasis, indicating that the transcriptional regulation of STAT1/2 could limit the development of OS." (PMID 40956299, 2025).
tumor (continued). "We analyzed the role of ICDRs in tumor immune microenvironment by using the previous data of single cell transcriptome, and we analyzed the distribution of several key genes (PSME2, TYMP, KLHDC7B, GBP5, EPSTI1, STAT1 and OAS2) in different cell types." (PMID 40259929, 2025). "Further, we examined the promoter methylation levels of DELMRGs and found that several genes (such as OAS2, KALRN, SLC16A7, PER2) had significantly lower methylation levels in tumor samples, while several genes (SLC6A3, CDO1, and SERPINC1) were significantly higher methylated." (PMID 37795453, 2023). "In our PPI analysis, the majority of the genes in the most closely connected module were significantly upregulated in M1 macrophages, including STAT1, OAS1, OAS2 and DDX5; thus, developing small molecule agonists for these proteins may enhance anti-tumor immunity." (PMID 33323552, 2020). "The invasive front (arrow) showed stronger GSN immunoreactivity than the central tumor in seven patients (35%; 4 patients with recurrence and 3 patients without recurrence), whereas OAS2 immunoreactivity was not different between invasive front and central tumor regardless of recurrence." (PMID 30148861, 2018). "IHC analysis of a separate set of tumor tissues from 20 patients (10 patients each with and without recurrence) detected cytoplasmic expression of GSN and OAS2." (PMID 30148861, 2018).
cancer (20 papers, 2010 to 2024). A tumor composed of atypical neoplastic, often pleomorphic cells that invade other tissues. "Out of these SNPs, several occur in genes associated with behavior (Scn10A), metabolism (Ppgca1b), cancer (Brca2), and immune response (Map3k1, OAS2, IL18R1)." (PMID 21668978, 2011). "Moreover, OAS2 overexpression was found to be significantly associated with a favorable prognosis in various cancers." (PMID 39416786, 2024). "Up-regulated expressions of the hypo-methylated gDMs in cancer were observed for OAS2, MX2, APOL3, ABHD8, RASSF1, SIGIRR, and SPRED2." (PMID 36329447, 2022). "In particular, the expression levels of genes, such as IFI6, MX1, IFIT1, IFIT3, ISG15, OAS1, and OAS2, which belong to the cancer-promoting ISG subset IRDS, were markedly increased." (PMID 35618021, 2022). "We note that other SNPs associated with CIN3/cancer included those in the OAS1, OAS2, and POLN genes." (PMID 20084279, 2010). "Previous studies supported the assertion that the upregulation of Oas2 could enhance resistance to DNA damage and improve cell viability in cancers." (PMID 36421815, 2022). "Extensive evidence supports the role of autophagy in the regulation of immune responses and cancer immunotherapy, whereas the role of OAS2 in autophagy remains unknown." (PMID 30148861, 2018). "The grading of all patients could only be combined for the gene OAS2 due to the fact that different genes were identified for the two sets of cancer patients." (PMID 28443095, 2017). "Hypo-methylated gDMs like MX2, OAS2, SPRED2, ADAP1, and SLC17A9 genes showed significant increased expression in cancer stage IV compared to stage I." (PMID 36329447, 2022). "Three genes, CD40, OAS2, and CXCR1, were identified as potential biomarkers of normal tissue toxicity in cancer patients after radiotherapy." (PMID 28443095, 2017). "In addition, TCGA data revealed that the expression level of OAS2 in cancer samples is significantly increased compared to normal (FDR < 0.01)." (PMID 38355581, 2024).
immune diseases (1 paper, 2023). "The expression and function of IFI44 and OAS2 still need further exploration and experimental verification, especially in chronic inflammatory and immune diseases." (PMID 37898694, 2023).
inflammatory myopathies (1 paper, 2023). "Using microarrays, IFIG expression levels (including ISG5, Mx1, OAS1, IFIT4, IFIT1, IFI44, OAS3, OAS2, IRF7, and IFI27) in muscle samples were higher in DM than in other inflammatory myopathies, such as inclusion body myositis, polymyositis, necrotizing myopathy, and myopathies with inflammation." (PMID 36979843, 2023).
renal disorders (1 paper, 2020). "Active SLE patients with renal disorders showed higher OAS2 and OASL expression in PBMCs, OAS3 and OASL expression in CD19+ B cells, and OAS3 expression in CD4+ T cells than patients without the symptoms (P<0.05)." (PMID 32321151, 2020).